CD151 (CD151 molecule (Raph blood group))
Diseases named in the same sentence as CD151 in open-access papers (continued):
Sharing a sentence is not in itself a finding about the gene and the disease.
colon carcinoma (9 papers, 2003 to 2021). "CD151 expression is closely related to the progression of breast, prostate and colon cancer; its expression is positively associated with the metastasis of breast and prostate cancers." (PMID 27556355, 2016). "CD151 is closely related to the progression of breast, prostate and colon cancer, promoting metastasis." (PMID 27556355, 2016). "Specifically, overexpression of CD151 enhances cell motility, invasion, and metastasis in colon cancer and fibrosarcoma cells." (PMID 22294188, 2012). "On the other hand, positive CD151 expression had a bad effect on the overall survival rate of patients with colon cancer (61.2 vs 74.9%, P=0.022)." (PMID 12838318, 2003). "As part of our evaluation of members of the TM4SF as possible prognostic predictors, we performed a retrospective study on the expression of the MRP-1/CD9 gene, the recently identified KAI1/CD82 gene and the CD151 gene in human colon cancer." (PMID 12838318, 2003). "The aim of this study is to clarify the clinical significance of the member of TM4SF (MRP-1/CD9, KAI1/CD82 and CD151) in human colon cancer." (PMID 12838318, 2003). "We have shown that the reduction of MRP-1/CD9 and KAI1/CD82 expression, and the increasing CD151 expression are indicators for a poor prognosis in patients with colon cancer." (PMID 12838318, 2003). "To verify whether CD151 is required for colon cancer progression, we investigated cell proliferation, migration and invasion in sh-CD151 HT29 and HCT116 cells." (PMID 33767593, 2021). "Upregulation of CD151 is found in many tumour types and CD151 overexpression was associated with poor prognosis in non-small cell lung, colon cancer, hepatocellular, pancreatic, oesophageal, and endometrial cancer." (PMID 22294188, 2012). "Anti-CD151 antibodies or CD151 mutants can selectively inhibit integrin α3 and α6-dependent cell migration, whereas upregulation of CD151 enhances experimental metastasis of colon carcinoma and fibrosarcoma cells." (PMID 21961047, 2011). "Interestingly, it was also found that the expression level of CD151 in the metastatic lesions was increased when compared with primary colon cancer tissues." (PMID 21505452, 2011). "In addition, no consistent findings have been reported as a prognostic indicator for CD151 gene in colon cancer." (PMID 12838318, 2003). "This is a first report describing about the relation between CD151 and colon cancer." (PMID 12838318, 2003). "Moreover, our present study showed that there was a significant difference between the overall survival rate for colon cancer patients with low CD151 expression and that of patients with CD151-positive tumours." (PMID 12838318, 2003). "However, the mechanism of CD151's effects in colon cancer progression remains largely unknown." (PMID 33767593, 2021). "Previous studies on epithelial cells have demonstrated that CD151 is upregulated by chronic exposure to TGF-β (hepatocyte cell line) and suppressed by hypoxia (colon cancer cell line)." (PMID 28473332, 2017). "We studied 146 colon cancer patients who underwent curative surgery and studied the expression of MRP-1/CD9, KAI1/CD82 and CD151 using reverse transcriptase – polymerase chain reaction and immunohistochemistry." (PMID 12838318, 2003). "As part of our evaluation of members of TM4SF as possible prognostic predictors, we further extended our study to the expression of CD151 and performed a retrospective study on the expression of CD151, MRP-1/CD9 and KAI1/CD82 in colon cancer." (PMID 12838318, 2003). "CD151 expression was significantly increased in 5 colon cancer tissue samples compared with paired non-cancerous samples as assessed by Western blot (P<0.05)." (PMID 33767593, 2021). "In agreement, CD151 mRNA levels were increased in colon cancer tissue specimens compared with paired non-cancerous ones as determined by qRT-PCR (n=32, P<0.05)." (PMID 33767593, 2021).
colon carcinoma (continued). "The classification of colon cancers according to MRP-1/CD9, KAI1/CD82 and CD151 expression might be useful in identifying patients for whom intensive adjuvant therapy is warranted." (PMID 12838318, 2003).
colorectal cancer (9 papers, 2010 to 2025). A primary or metastatic malignant neoplasm that affects the colon or rectum. "In colorectal cancer patients, CD151 expression is high in early disease stage, but decreases with increasing invasion and metastasis caused by hypoxia 13,14." (PMID 33767593, 2021). "CD151 impacts various signaling pathways in different cancers, and promotes colorectal cancer (CRC) cell malignancy by yet undefined mechanisms." (PMID 33767593, 2021). "In colorectal cancer CD151 is differentially expressed between normal (high expression), primary (low expression), and metastatic (high expression) tissue." (PMID 22272937, 2012). "Similar to both breast and colorectal cancers, CD151 staining in ovarian tumors was seen to be both membranous and cytoplasmic." (PMID 22272937, 2012). "High CD151 expression confers poor prognosis in breast, pancreatic and colorectal cancer." (PMID 21505452, 2011).
glioblastoma (9 papers, 2015 to 2024). The most malignant astrocytic tumor (WHO grade IV). "It was reported that CD151-α3β1 integrin complex can interact with EGFR to promote tumor invasion of glioblastoma, and integrin-associated CD151 can promote progression and metastasis of tumor mediated by ErbB2." (PMID 34108040, 2021). "Here, we report clinical and functional analyses of CD151 and its associated α3 integrin in glioblastoma." (PMID 26377974, 2015). "Together, these available observations implicate that, like its associated LB integrins, CD151 is a potential key player in the progression of glioblastoma." (PMID 26377974, 2015). "Results from the present study strongly support the prognostic and therapeutic potential of CD151-α3β1 integrin complexes and their associated pathways for glioblastoma." (PMID 26377974, 2015). "As such, our findings provide crucial evidence of CD151-integrin complexes and associated pathways as prognostic markers and therapeutic targets for glioblastoma or other aggressive gliomas." (PMID 26377974, 2015). "Together, these data illustrate that CD151 and its associated LB integrins form protein complexes and cooperate to promote the invasiveness of glioblastomas." (PMID 26377974, 2015). "Together, these findings provide strong clinical, cellular and molecular evidence that CD151-α3β1 integrin complexes and associated pathways are crucial players in the progression of glioblastoma or other malignant gliomas." (PMID 26377974, 2015). "The current study provides strong clinical evidence for the close link between CD151 or its associated α3β1 integrin and the malignancy of human glioblastoma." (PMID 26377974, 2015). "How CD151 and its associated LB integrins are associated with the aggressiveness of glioblastoma, however, still remains largely unclear, particularly at the clinical, cellular, and signaling levels." (PMID 26377974, 2015). "Thus, identification of a stem cell-related link will shed new light on the importance of CD151-LB integrin complexes or associated TEMs in glioblastoma malignancy." (PMID 26377974, 2015). "Conversely, the CD151-α3β1 complex can synergize with EGFR to enhance glioblastoma cell metastasis via the activation of FAKY397 and GTPase signaling pathways." (PMID 35524311, 2022). "Consistent with this notion, we and others have observed a strong tumor-promoting role of CD151 in glioblastoma." (PMID 33919420, 2021). "Results from these analyses demonstrate that CD151 and α3β1 integrin are key drivers of glioblastoma aggressiveness, and serve as independent prognostic markers and promising therapeutic targets." (PMID 26377974, 2015). "Rather, CD151 and α3β1 integrin drive the aggressiveness of glioblastoma by accelerating tumor cell motility and invasiveness." (PMID 26377974, 2015). "These in vitro and ex vivo observations demonstrate that CD151 promotes glioblastoma progression by promoting tumor cell motility and invasiveness, rather than impacting cell proliferation or tumor growth." (PMID 26377974, 2015). "The number of CD151-positive tumors in the glioblastoma group, that is, WHO grade IV gliomas, was more than two-fold higher than their low-grade counterparts." (PMID 26377974, 2015). "Our FACS analyses indicated that CD151 and LB integrins were highly expressed across a panel of glioblastoma cell lines." (PMID 26377974, 2015). "It is of clinical significance to know how expression of CD151 or α3β1 integrin is markedly elevated in glioblastomas at both the mRNA and protein levels." (PMID 26377974, 2015). "Our biochemical analyses reveal the presence of CD151-α3β1 integrin complexes in glioblastoma cells." (PMID 26377974, 2015). "Results from our studies support a close link between CD151-α3β1 integrin complexes and the aggressiveness of glioblastomas." (PMID 26377974, 2015).
glioblastoma (continued). "In line with these in vitro observations, CD151 knockdown extended the survival of tumor-bearing mice with orthotopic LN229 glioblastoma xenografts (p < 0.05), even though minimal change occurred in tumor growth." (PMID 26377974, 2015). "Results from our analyses showed that CD151 and α3 integrin were significantly elevated in glioblastomas at both protein and mRNA levels, and exhibited strong inverse correlation with patient survival (p < 0.006)." (PMID 26377974, 2015). "It is worth noting that the pro-malignant function of CD151-integrin complexes in glioblastoma occurs in the context of cell-ECM interaction, consistent with prior studies in other cancer types." (PMID 26377974, 2015). "Collectively, our findings provide clinical, molecular and cellular evidence of CD151-α3β1 integrin complexes as promising prognostic biomarkers and therapeutic targets for glioblastoma." (PMID 26377974, 2015). "Intriguingly, CD151 knockdown in multiple glioblastoma lines had minimal effect on the surface expression of its associated partners, as determined by our FACS analyses." (PMID 26377974, 2015). "Given the high expression of multiple laminin isoforms in glioblastoma cells, CD151-α3β1 integrin complexes may act in an autocrine fashion." (PMID 26377974, 2015). "Moreover, because normal brain tissues are highly enriched in laminins, the pro-malignant roles of CD151-α3β1 integrin complexes in glioblastomas are likely strengthened by the tumor microenvironments." (PMID 26377974, 2015). "Of note, CD151 may also drive glioblastoma malignancy by affecting the stemness property of glioma cells." (PMID 26377974, 2015). "In summary, our study demonstrates that CD151 and its associated α3 integrin are markedly elevated in malignant gliomas, and synergize with EGFR-dependent signaling pathways to drive the aggressive behaviors of glioblastoma cells." (PMID 26377974, 2015). "Furthermore, we found that CD151-α3β1 integrin complexes signal through Graf (ARHGAP26)/small GTPase-dependent pathways in glioblastoma cells." (PMID 26377974, 2015). "Our data also implicate that the impact of CD151-α3β1 integrin complexes on the malignant behaviors of glioblastomas may occur in the context of TEMs." (PMID 26377974, 2015). "As such, our findings support CD151 and α3β1 integrin as potential biomarkers for glioblastoma." (PMID 26377974, 2015). "Given the emerging link of these molecules to the stemness of glioblastoma, targeting CD151-LB integrin complexes may also provide an effective means against tumor recurrence." (PMID 26377974, 2015). "As these oncogenic events frequently occur in glioblastoma, the cooperation between CD151-α3β1 integrin complexes and EGFR detected in the current study may only reflect part of broad contributions of such complexes to the aggressiveness of such disease." (PMID 26377974, 2015). "However, it is still unclear as to the mechanism of CD151 mRNA upregulation in glioblastomas." (PMID 26377974, 2015). "The strong cooperation or synergy between CD151-LB integrins complexes and EGFR in glioblastomas revealed by our study is of high translational significance, as aberrant activation of this RTK occurs in >70% gliomas." (PMID 26377974, 2015). "Collectively, our data suggest that CD151-α3β1 integrin complexes and EGFR converge at FAK and Graf (ARHGAR26) to drive the motility and invasiveness of glioblastoma." (PMID 26377974, 2015). "Our analyses of TCGA glioblastomas reveal minimal change in the copy number of CD151 or α3 integrin gene (data not shown), implicating a mechanism other than gene amplification or copy gain." (PMID 26377974, 2015). "Together, these observations indicate a crucial role of the Graf (ARHGAP26)/Rac1/Cdc42 axis, not DOCK180 or ELMO1, in CD151-α3 integrin complex-mediated signaling in glioblastoma." (PMID 26377974, 2015).
glioblastoma (continued). "Although the RGD-based integrins, such as α5β1 integrin, are shown to promote survival and drug resistance of glioblastoma cells, disruption of CD151 or α3β1 integrin appears to have minimal influence on the proliferation or survival of glioblastoma cells (data not shown)." (PMID 26377974, 2015). "In addition, our observation of the activation of FAK as reflected by the enhanced phosphorylation of Y397 residue upon the engagement of laminin-5 and CD151-integrin complexes is in line with the pro-malignant role of this non-receptor tyrosine kinase in glioblastomas." (PMID 26377974, 2015).
osteosarcoma (9 papers, 2010 to 2024). A usually aggressive malignant bone-forming mesenchymal neoplasm, predominantly affecting adolescents and young adults. "Previous studies have suggested an association between CD151 and distinct consequences in osteosarcoma development." (PMID 36209197, 2022). "Previous studies have suggested an association between CD151 and distinct consequences in osteosarcoma tumorigenicity." (PMID 36209197, 2022). "Further studies are necessary to fully explore the diagnostic and prognostic value of determining CD151 expression in osteosarcoma patients." (PMID 27556355, 2016). "However, the specific molecular mechanism underlying the regulatory role of CD151 in the metastasis of osteosarcoma and the efficacy of therapy targeting CD151 remain to be elucidated in further studies." (PMID 27556355, 2016). "Importantly, the metabolic phenotype reprogrammed by CD151 could further serve as a point of intervention and biomarker for osteosarcoma progression and therapeutic susceptibility." (PMID 36209197, 2022). "CD151 has been demonstrated to promote osteosarcoma pulmonary metastasis, and depletion of CD151 in cancer cells significantly suppressed integrin β1, FAK, p-mTOR, and p70s6 levels as well as Akt, p56 and p38 phosphorylation." (PMID 38389703, 2024). "Collectively, these data demonstrated the in vivo efficacy of myriocin in inhibiting osteosarcoma growth and indicated that CD151 expression was a potentially useful biomarker for predicting the efficacy of sphingolipid metabolism inhibition." (PMID 36209197, 2022). "Western blot analysis was used to examine the expression of SPTLC1 in osteosarcoma cells, and the results showed that the knockout of CD151 remarkably decreased, whereas CD151 overexpression significantly increased SPTLC1 protein levels." (PMID 36209197, 2022). "To evaluate the therapeutic potential of targeting CD151 in vivo, we first detected CD151 mRNA expression levels in several osteosarcoma PDX models." (PMID 36209197, 2022). "Based on the finding that CD151 is a key regulator of sphingolipid metabolism, we conducted an initial translational experiment in osteosarcoma." (PMID 36209197, 2022). "The application of sphingolipid metabolism pathway inhibitors will provide new insights into the development of novel CD151-based targeted therapies for osteosarcoma." (PMID 36209197, 2022). "The present study indicates that CD151 is critically important for regulating sphingolipid metabolism in osteosarcoma." (PMID 36209197, 2022). "Taken together, our transcriptomic and metabolomic measurements identified CD151 as a mediator of the reprogramming of sphingolipid metabolism in osteosarcoma cells." (PMID 36209197, 2022). "Overexpression of CD151 significantly increased c-myc transcriptional activity in osteosarcoma cells." (PMID 36209197, 2022). "In this study, we demonstrated that CD151 reprograms sphingolipid metabolism that aids cell growth in osteosarcoma through global metabolomics, transcriptomics, and functional analysis in vitro and in vivo." (PMID 36209197, 2022). "We conducted preliminary osteosarcoma translational experiments in light of our finding that CD151 was a key mediator of sphingolipid metabolism." (PMID 36209197, 2022). "CD151 has been recognized as a prognostic marker and therapeutic target for osteosarcoma but has been less explored for direct targeting of molecular inhibitors." (PMID 36209197, 2022). "In this study, we conducted an integrated transcriptomic and metabolomic analysis of osteosarcoma and identified sphingolipid metabolism as the top CD151-regulated pathway." (PMID 36209197, 2022). "Our work demonstrates that CD151 is a promising biomarker for predicting the effectiveness of sphingolipid metabolism inhibitors in osteosarcoma." (PMID 36209197, 2022).